HIF1A (hypoxia inducible factor 1 subunit alpha)
Diseases named in the same sentence as HIF1A in open-access papers (continued):
Sharing a sentence is not in itself a finding about the gene and the disease.
tumor (continued). "Tumor hypoxia induces stabilization of a transcription factor, hypoxia‐induced factor‐1A (HIF‐1A), that drives transcriptional responses in both stromal cells and cancer cells, thus promoting cancer progression." (PMID 35658112, 2024). "It is well known that hypoxic conditions in the TME sustain tumour progression and survival, and the principal hypoxia mediator is hypoxia-inducible factor 1 alpha (HIF1α)." (PMID 38339377, 2024). "The HIF-1α/HRE complex directly upregulates VEGFR-1 expression in tumor cells, further amplifying VEGF signaling." (PMID 38542288, 2024). "Another important indicator of tumor blood vessel normalization is the alleviation of hypoxia, so we proceeded to assess HIF-1α expression in tumor tissues via immunohistochemistry staining." (PMID 38616190, 2024). "Increased HIF-1α promotes tumor vascular remodeling, epithelial-mesenchymal transformation (EMT), and OS cells invasiveness; this leads to distant metastasis of OS cells." (PMID 38327979, 2024). "For the HIF-1α expression, the in vivo hypoxia microenvironment in tumor tissue pretreated with various formulations was investigated by immunohistochemistry (IHC)." (PMID 39339168, 2024). "HIF1α promotes tumor progression by regulating the transcription of various genes involved in metabolic reprogramming, metastasis, chemotherapy resistance, and immunosuppression." (PMID 38769340, 2024). "The hypoxic tumor microenvironment, facilitated by factors such as HIF-1α, significantly influences UPS progression." (PMID 38999251, 2024). "In tumor tissue, nanoparticles 54b&SRF@BSA decreased the level of HIF-1α protein ( ~ 25% relative to the control) after irradiation via inhibition of mitochondrial respiration and normalization of the tumor vasculature." (PMID 39138299, 2024). "Chemotherapy and radiotherapy: HIF-1α antagonism can enhance the tumor’s response to chemotherapy and radiotherapy, as it compromises cell survival signaling." (PMID 39493156, 2024). "Mitochondrial dysfunction has been shown to decrease HIF-1α stabilization and improve the effectiveness of hypoxic tumor therapy." (PMID 39682267, 2024). "USP29 stabilizes MYC and hypoxia-inducible factor 1-alpha (HIF1α); therefore, it enables tumor cells to respond to both normoxia and hypoxia." (PMID 39664521, 2024). "Due to the diminished capacity of tumor cells to take up aspartate compared to other metabolites, this counteracting effect of the glutamine production of aspartate by HIF-1α can significantly inhibit the proliferation of tumor cells." (PMID 38172980, 2024). "An earlier publication demonstrated that acute hypoxia correlates with transient increases in HIF-1α levels, elevated tumor numbers in the lung, transiently increased permeability in pulmonary microvessels and increased iNOS expression." (PMID 38791951, 2024). "Meanwhile, curcumin suppressed tumor immune escape by inhibiting the TLR4/HIF-1α/PD-L1 pathway in the inflammatory environment of CRC." (PMID 38612546, 2024). "New findings of our meta-analysis indicated the statistical associations between positive HIF1A expression and other clinicopathological features, including Borrmann stage progression, positive VEGF protein expression, and tumor sizes." (PMID 38877062, 2024). "Obtaining the expression information of HIF-1α before treatment is helpful to quantitatively evaluate the degree of hypoxia of the tumor, thus helping to predict the treatment response or adjust the treatment plan as soon as possible." (PMID 39723370, 2024). "Several studies have shown that high expression of VEGF receptor (VEGFR) in a hypoxic environment can induce tumor angiogenesis, and Hypoxia inducible factor 1 alpha (HIF-1a) induces the production of multiple mediators in hypoxia." (PMID 39156971, 2024). "We found that TLR4, together with HIF-1α and PD-L1, was negatively expressed in adjacent normal tissue but positively expressed in tumor tissue, implying a positive correlation between TLR4 and HIF-1α/PD-L1." (PMID 38612546, 2024).
tumor (continued). "Hypoxia-inducible factor-1α (HIF-1α) is severely reported as a critical factor for tumour progression." (PMID 38698968, 2024). "Immunotherapy: Targeting HIF-1α can indeed modify the tumor microenvironment with the possible enhancement of immunotherapeutics." (PMID 39493156, 2024). "In the hypoxic tumor microenvironment, HIF1A binds to the PD-L1 promoter region, upregulating PD-L1 in myeloid-derived suppressor cells and tumor cells." (PMID 38877062, 2024). "Vascular endothelial growth factor (VEGFA), a key protein in tumor angiogenesis, is a critical downstream target of HIF1α signaling and plays an important role in tumor invasion and metastasis." (PMID 38339062, 2024). "In this paper, we review the newly discovered central role of HIF-1α in regulating the metabolic reprogramming of tumor cells in recent years and review the current research status of chemotherapeutic drugs using HIF-1α as an entry point." (PMID 39496001, 2024). "Particularly under hypoxic conditions in tumors, the expression of HIF-1α activates genes that promote tumor growth, resulting in more invasive tumor phenotypes." (PMID 39766299, 2024). "The hypoxic conditions induced by IRI lead to HIF-1α activation, which, in turn, promotes glycolysis, angiogenesis, and other pathways that support tumor growth and spread." (PMID 39199562, 2024). "We have also provided evidence that ZBTB18 Nte-SF, by positively affecting HIF1A target gene expression, acquires tumor promoting capabilities, which are opposite to the tumor suppressor role of full-length ZBTB1819." (PMID 39516530, 2024). "Inhibiting the expression of VEGF and HIF-1α effectively suppresses angiogenesis and curbs tumor progression." (PMID 39124760, 2024). "In melanoma, the upregulation of GPx3 plays a role in regulating ROS levels by inhibiting the expression of HIF1α, which is upregulated in various human cancers and plays a key role in driving tumor growth, invasion, and metastasis." (PMID 39125992, 2024). "Under pseudohypoxia conditions, tumor cells use Hif-1α to promote invasion, metastasis, therapeutic resistance, and angiogenesis as adaptations to these stress conditions." (PMID 39518121, 2024). "Prolonged hypoxia induces hypoxia-inducible factor 1α (HIF-1α) upregulation, which, in turn, promotes angiogenesis, and tumor cell permeation and proliferation, mediating cancer recurrence." (PMID 39199562, 2024). "Both HIF-1α and HIF-2α contribute to tumor hypoxia, but HIF-1α appears to be more prominently involved in energy metabolism and angiogenesis." (PMID 38542288, 2024). "HIF1α’s influence extends beyond oxygen adaptation, playing a crucial role in tumor growth and metastasis by upregulating factors that promote cell division and inhibit apoptosis." (PMID 39697237, 2024). "After IDH1 gene knockdown, HIF1a expression is upregulated, and the glycolysis level of tumor cells is increased, which increases their sensitivity to glucose." (PMID 38622131, 2024). "Hypoxia and HIF-1α upregulated under hypoxic conditions promote tumor cell survival and chemotherapy resistance in many malignancies." (PMID 39768123, 2024). "In multiple cancer cell models, NRF2 silencing has been shown to reduce HIF-1α levels, resulting in the suppression of HIF-1α-mediated cell proliferation, angiogenesis, tumor growth, and migration/invasion." (PMID 38424190, 2024). "With respect to the within-group distribution, some genes have a narrow expression range (for example, KRT, HIF1A in both tumour and stromal compartments of p16+/HPV+ tumours, and PSMB10, B2M in the stromal compartment for all p16/HPV subgroups)." (PMID 39328208, 2024). "Serum HIF-1α level (P < 0.05) and tumor HIF-1α protein level (P < 0.001) were reduced after ozone treatment or the radiation+ozone treatment compared to those after radiation." (PMID 38842109, 2024).
tumor (continued). "ccRCC is associated closely with mutations in the VHL gene that lead to the activation of HIF-1α and HIF-2α via a pseudohypoxia mechanism, resulting in the transcription of genes involved in tumor progression." (PMID 39399506, 2024). "To further confirm the role of the PI3K/AKT/mTOR/HIF-1α signaling pathway in TGFBI-mediated tumor promotion, we used the AKT activator SC79 to treat 786-O cells transfected with TGFBI siRNA." (PMID 39068456, 2024). "Specific inhibition or knockdown of LDHA and HIF1A can restore sensitivity to therapeutic agents such as bortezomib and can also inhibit tumor growth induced by altered metabolism." (PMID 39025844, 2024). "Hypoxia‐inducible factor 1‐alpha (HIF‐1α), stabilized under hypoxic conditions common in tumours, promotes glycolysis and suppresses mitochondrial respiration." (PMID 39601114, 2024). "This review article aims to present a thorough summary of the processes via which HIF-1α promotes tumor hypoxia and growth." (PMID 39493156, 2024). "HIF-1α inhibitors affect the conditions in the tumor microenvironment and thereby improve the ability of the host immune system to perceive and destroy cancer cells." (PMID 39493156, 2024). "HIF-1α upregulates the expression of various immunosuppressive molecules in tumor cells, including galectin-9 (Gal-9)." (PMID 38542288, 2024). "These ROS can further stabilize HIF1α, damage mitochondria, and contribute to changes in tumor signaling." (PMID 38929778, 2024). "The HDAC inhibitor SAHA has been found to decrease HIF1α levels in tumor cell lines via direct acetylation of heat shock protein 90 (Hip90), a HIFα chaperone protein, using HDAC6." (PMID 38279330, 2024). "Tumor hypoxia and the upregulation of HIF-1α gene expression upregulate the expression of multidrug-resistant proteins and have been suggested to be the main cause of multidrug resistance." (PMID 39768123, 2024). "Protumorigenic factors associated with hypoxia and angiogenesis, like HIF1A and VEGFA, as well as genes related to a pro-tumoral phenotype, such as SPP1 and TGFB2, were highly expressed in this macrophage found in the tumor context." (PMID 38972873, 2024). "HIF-1α is a critical mediator of intratumoral heterogeneity, tumor progression, and resistance to therapy in hypoxic tumors." (PMID 38945955, 2024). "In contrast, inhibition of IDH2 in TNBC cells would be expected to cause a major disruption of α-KG reductive flow, a decrease in HIF1α, and a suppression of tumor growth." (PMID 38658533, 2024). "Application of the HIF‐1A blocker or miR‐210‐3p inhibitor showed a notable suppression of tumor cell growth in 3D spheroids along with the induction of CCL2 expression, monocyte migration, and switching macrophage polarity." (PMID 35658112, 2024). "The notable rise in HIF1A expression, key in regulating responses to low oxygen levels, highlights its likely role in neovascularization and the aggressive behavior of tumor cells in the hypoxic areas of ESCC." (PMID 39468431, 2024). "Under hypoxic condition, WTAP is required for the expression of two major hypoxic markers, HIF1α and HIF1β, underlying the relevant role of MALAT1-WTAP axis in regulating adaptation of the tumor cells to hypoxia, a fundamental step in tumor progression." (PMID 38862471, 2024). "Lactic acid plays a role in stabilizing HIF-1α, thereby mediating the promotion of angiogenesis and tumor growth." (PMID 38672455, 2024). "Our results suggest that HNSCC patients with hypermethylation in the HIF1A promoter region in normal tissues display lower mRNA levels of this gene in normal tissues compared to hypomethylated tumor ones." (PMID 38928200, 2024). "In parallel, data from both MRI–PET imaging and HIF-1α or VEGF immunophenotypes can distinguish between GBM tumor progression and pseudoprogression." (PMID 39055895, 2024). "Due to its involvement with tumor genesis, it is frequently targeted by anti-cancer therapies as blocking HIF-1α can inhibit tumor growth." (PMID 38333571, 2024).
tumor (continued). "Tumor immune escape, where cancer cells avoid detection and destruction by the host immune system, is facilitated under hypoxic conditions through HIF-1α overexpression." (PMID 38799423, 2024). "The activation of IDH1 by Scu can significantly increase the level of α-KG in tumor tissue, downregulate the HIF1a signaling pathway, and activate the tumor immune microenvironment in vivo." (PMID 38622131, 2024). "For instance, lactate production through glycolysis in early tumor stages promotes TAM polarization via HIF-1α." (PMID 39086383, 2024). "Bioinformatical analysis reveals that HIF1A is correlated with the increased tumor immune signature and more aggressive tumor phenotypes." (PMID 38928200, 2024). "Another study showed that SIRT1 can inhibit tumor progression by inhibiting the activity of HIF-1α and reducing the ability of KIRC cells to adapt to hypoxic environments." (PMID 39845948, 2024). "In response to this increased energy demand, tumors activate various adaptive mechanisms, including the upregulation of HIF-1α, leading to an increase in tumor angiogenesis and a more abundant tumor microcirculation." (PMID 39525622, 2024). "ii) significantly blocking the intracellular HIF-1α signaling pathway to inhibit distant tumor metastasis." (PMID 38280861, 2024). "HIF-1α is a key factor that is responsible for regulating the energy supply in tumor cells under both normoxic and hypoxic conditions." (PMID 38904007, 2024). "Acetate supplementation, by restoring [acetyl CoA] and H3K9Ac expression in the promoter and regulatory regions of Ifng gene in Hif1α–/– T cells, enhances Ifng transcription and rescues IFN-γ production as well as tumor-killing capacity of Hif1α–/– T cells." (PMID 39477954, 2024). "Specifically, the LIMD1 gene responds to hypoxia through an HIF1-α response element in its promoter and, as a protein, acts as a scaffold to stabilize the PHD2/VHL/HIF-1α degradation complex, in this sense working as a tumor suppressor." (PMID 38794149, 2024). "In BC cells, HIF-1α plays a critical role in stimulating the metastasis of primary tumor to distant organs, which is closely related to patient mortality." (PMID 38697993, 2024). "The other carcinogenic effect of HPV-16 oncoproteins in NSCLC is the promotion of tumor angiogenesis both in vitro and in vivo, and correspondingly, the enhanced expression of HIF-1α and VEGF." (PMID 39409943, 2024). "Hypoxic conditions in solid tumors lead to the upregulation of HIF-1α, which promotes tumor progression and metastasis." (PMID 39407454, 2024). "IHC staining of subcutaneous tumour tissues indicated that the protein level of HIF‐1α was reduced in the LYRM2 konckdown group." (PMID 39661026, 2024). "It is worth noting that metastasis and tumor progression are multifactorial processes, with HIF-1α being one of several contributing elements." (PMID 39595235, 2024). "SMURF2, a tumor suppressor, regulates various cellular processes beyond degrading HIF1α, including the ubiquitin-proteasome system’s stability, essential for normal cell function." (PMID 39697237, 2024). "In this regard, we have observed that adipose cell-derived sEVs can promote tumor aggressiveness by enabling multiple phenotypic and metabolic changes, including reduced docetaxel responsiveness and enhanced Akt/HIF-1α-dependent glycolysis." (PMID 39316264, 2024). "A transient glycolytic activation triggers sustained CA12 expression on tumor-infiltrating monocytes and macrophages via autocrine cytokines and HIF-1α signaling pathways." (PMID 39430253, 2024). "Specifically, the activation of this pathway influences the activities of key enzymes such as HK2, ATP-citrate lyase (ACL), and the stabilization of hypoxia-inducible factor 1-alpha (HIF1a), ultimately enabling the tumor cells to meet their energy needs." (PMID 38479191, 2024). "Organismal tissues under hypoxia can induce autophagy in tumor cells through the mediation of HIF1α." (PMID 38315272, 2024).
tumor (continued). "The results revealed the colocalization of IL21-AS1 with CD24 and HIF-1α in the cytoplasm, and the signals were specifically increases in hypoxic tumour regions." (PMID 38702326, 2024). "For example, CHIP can inhibit tumor growth by degrading oncogenic proteins such as c-Myc, src-3, HIF-1α, and pAKT." (PMID 38272235, 2024). "HIF-1α plays a pivotal role in regulating these processes, enabling cancer cells to adapt to adverse microenvironments and promoting tumor aggressiveness." (PMID 39493156, 2024). "Our findings interpret that, less is the expression of LDH 3, 4 and 5 in tumor tissue Once again this is also related to the HIF1a responses noticed in the current study." (PMID 39132498, 2024). "Hypoxia-inducible factor-1a is an important transcription factor that has been proven to act as a master regulator of quite a few genes, especially in the hypoxic tumor microenvironment where HIF-1a thrives." (PMID 38257813, 2024). "We further conducted in vivo experiments to explore the involvement of MKLN1-AS in mediating the promotive effects of HIF-1α on tumor growth and metastasis." (PMID 38740637, 2024). "The VEGF-A/HIF-1α axis regulates tumor progression, as the hypoxic upregulation of VEGF-A is required to promote the angiogenic phenotype." (PMID 39199545, 2024). "HIF-1α-mediated programmed death cell ligand 1 expression has been observed in tumor cells, dendritic cells, and macrophages." (PMID 38542288, 2024). "In tumor resection specimens of EC patients, the overall percentages of FAK+, CD44+, HIF-1α+, and Ki67+ cells were higher in tumor nests than in the tumor stroma, with Ki67+ cells reaching statistical significance (p < 0.001)." (PMID 38727811, 2024). "Carbonic anhydrase IX (CAIX) is a downstream gene of HIF1α signaling, induced under hypoxic conditions and is widely available at the tumor site." (PMID 38361941, 2024). "The goal of this trial was to evaluate the modulation of HIF-1α mRNA and tumor response of patients with refractory solid tumors." (PMID 38396737, 2024). "HIF1A, one of the most critical genes affecting tumor cell hypoxia tolerance, showed a positive correlation with TOR1B expression in BLBC samples from the TCGA database (ρ=0.4, p < 0.01), indicating co-expression between the two." (PMID 38842687, 2024). "The elucidation of SMURF2’s role in HIF1α regulation opens potential strategies for cancer therapy, particularly in hypoxia-driven tumors where HIF1α plays a key role in tumor aggressiveness, metastasis, and resistance to therapy." (PMID 39697237, 2024). "High lactate expression also stabilizes HIF1α in macrophages to promote the expression of a HIF1α-stabilizing lncRNA, which is then transported back to tumor cells via extracellular vesicles." (PMID 38216787, 2024). "In line with reduced IFN-γ production in Hif1α–/– T cells, they were less able to kill tumor cells than WT T cells." (PMID 39477954, 2024). "The VHL protein reduces tumor formation via modification of multiple chemical signaling pathways, the most well studied of which being its role in HIF-1α regulation." (PMID 37883464, 2024). "It has been established that HIF-1α regulates oxygen homeostasis in the tumor microenvironment and can elevate COX2 expression by regulating it at transcriptional level." (PMID 38612478, 2024). "The role of HIF-1α in inducing cell cycle arrest during hypoxia varies depending on the specific context and tumor type being studied." (PMID 38399410, 2024). "When tumor cells become resistant to Docetaxel, HIF-1α protein expression increases, and this is thought to be a mechanism of resistance to therapy for the cell." (PMID 38213726, 2024). "Among the tumor tissues, 40 samples (40.40%) exhibited nuclear expression of HIF-1α, while 59 samples (59.60%) showed its absence." (PMID 38610951, 2024). "Knockdown of HIF-1α abrogates this effect of hypoxia and significantly impairs the tumor-initiating ability of BC cells." (PMID 38697993, 2024).